EGFR (epidermal growth factor receptor)
Diseases named in the same sentence as EGFR in open-access papers (continued):
Sharing a sentence is not in itself a finding about the gene and the disease.
diabetes (continued). "However, recent data from our laboratory showed that specific inhibition of ErbB2 receptor with AG825 or siRNA had similar vascular effects as a dual EGFR/ErbB2 inhibitor implying that ErbB2 rather than EGFR may be the predominant signaling pathway involved in diabetes-induced vascular dysfunction." (PMID 26536590, 2015). "Additionally, there is also evidence in the non-diabetic vasculature that acute EGFR signaling may mediate the contractions of GPCR ligands such as Ang II and endothelin (ET-1) that also play an important role in mediating diabetes-induced vascular dysfunction." (PMID 34408653, 2021).
Skin rash (145 papers, 2003 to 2026). A red eruption of the skin. "Although previous studies reported that skin rash induced by EGFR-TKIs was associated with better outcomes, the results obtained herein indicated that it was not a prognostic factor." (PMID 37221285, 2023). "Herein, using a normal human keratinocyte cell line (HaCaT cells) and human skin squamous cell carcinoma cell line (HSC-1), we aimed to explore the mechanisms underlying the relieving effects of MKH against skin rashes caused by EGFR inhibitors." (PMID 38092882, 2023). "The aim of this study was to explore the underlying mechanisms governing the relieving effects of MKH against skin rashes caused by EGFR inhibitors." (PMID 38092882, 2023). "An example includes the skin rash caused by EGFR inhibitors by the blockade of EGFR in keratinocytes." (PMID 36769861, 2023). "Epidermal growth factor receptor (EGFR) inhibitors frequently cause severe skin rash as a side effect, which is a critical burden for patients who continuously receive drug treatments." (PMID 38092882, 2023). "Large racial differences can mislead the calculation of the preset threshold and cause failure to achieve the primary endpoint, as skin rash during EGFR‐TKI treatment is known to occur more frequently in Asians than in non‐Asians." (PMID 37269194, 2023). "The drugs typically used in the EGFR inhibitor-associated skin rash, such as etracycline, doxycycline, minocycline and corticosteroid, all have obvious side effects after long-time use." (PMID 36165327, 2022). "At the same time, the side effects of EGFR-TKIs, including fatigue, loss of appetite, diarrhea, pruritus, and skin rash, were reduced." (PMID 35431966, 2022). "Antibiotics and corticosteroids are usually used to treat the EGFR inhibitor-associated skin rash, with prominent side effects over long-time use." (PMID 36165327, 2022). "Generally, topical steroid cream or ointment is prescribed for the treatment of EGFR inhibitor-associated skin rash, especially for acneiform rash." (PMID 36165327, 2022). "The risk of serious skin toxicities involving rash or dermatitis was substantially higher with EGFR inhibitor-based chemotherapy: cetuximab-based chemotherapy (RR 13.64; 95% CI 7.04–26.43) or panitumumab-based chemotherapy (RR 22.42; 95% CI 10.18–49.34)." (PMID 35954563, 2022). "This is probably one of the effective mechanisms of PZH Unguentum Compositum for treating skin rash caused by EGFR-TKI." (PMID 36165327, 2022). "Skin rash is frequently associated with the administration of epidermal growth factor receptor (EGFR) inhibitors, including tyrosine kinase inhibitors, such as gefitinib and erlotinib, and anti-EGFR monoclonal antibodies, such as cetuximab and panitumumab." (PMID 34441007, 2021). "For example, EGFR inhibition frequently causes skin rash and diarrhea, which can be especially severe in the radiation field, when the effects add up with (chemo-) radiation induced erythema/mucositis." (PMID 32903756, 2020). "Molecular targeting therapies often cause characteristic adverse effects, such as skin rash during anti-epidermal growth factor receptor (EGFR) therapies, making treatment continuation difficult." (PMID 31703435, 2019). "Skin rash is associated with all EGFR inhibitors and is the most frequently associated with cetuximab/CMAB009." (PMID 31126331, 2019). "Recently, there has been a focus on identification of patients with increased risk of developing EGFR inhibitor-induced rash." (PMID 30619755, 2018). "Dermatologic toxicities, especially akne-like skin rash, are the most common side-effects associated with anti-epidermal growth factor receptor (EGFR) therapy." (PMID 29285233, 2017). "An association between the development of skin rash and efficacy has been explored in several studies using EGFR-targeted therapies." (PMID 28445400, 2017). "Research suggests that the presence and severity of skin rash is associated with improved clinical efficacy in patients receiving EGFR inhibitors." (PMID 27893423, 2016).
Skin rash (continued). "Because osimertinib has activity against sensitizing EGFR mutations and is associated with reduced skin rash and diarrhea AEs, it has also been tested as a first-line treatment for metastatic EGFR mutation-positive NSCLC." (PMID 27912760, 2016). "TKIs are an effective targeted therapy for advanced NSCLC patients with activating mutations in EGFR but can also cause ADRs, such as skin rash and diarrhea." (PMID 26988277, 2016). "In order to elucidate the immune-mechanism of skin rash caused by EGFR inhibitors, we first investigated the modulatory effects of erlotinib, one of EGFR inhibitors, on the expression pattern of antigen presenting molecules and PD-L1 on skin keratinocytes." (PMID 27467256, 2016). "Treatment-related adverse effects (diarrhea, acne, and rash) associated with EGFR/HER1 blocking TKIs were more common in dacomitinib compared with erlotinib." (PMID 25674538, 2015). "Neither meta-analysis provided strong evidence that the use of an antibiotic reduced the incidence of rash associated with treatment with EGFR-targeted agents." (PMID 23801914, 2013). "The EGFR inhibitors have become a valid antitumor therapy in many cancers and associated with their use is the commonly reported skin rash and other dermatologic toxicities." (PMID 22997576, 2012). "Diarrhea and skin rash are considered class effects associated with EGFR inhibition, while hypertension, proteinuria, and bleeding events are well-established class effects of anti-VEGF therapy." (PMID 22878519, 2012). "The EGFR inhibitor–associated rash can produce pruritus, which affects approximately half of all patients." (PMID 25031940, 2012). "In genotyping analysis, EGFR intron 1 dinucleotide repeat polymorphism was associated with the occurrence of skin rash in patients who received gefitinib treatment." (PMID 24212826, 2011). "The skin rashes caused by EGFR-TKIs are dose-dependent, and reduction of the dosage usually ameliorates the rashes." (PMID 24212826, 2011). "In addition, aspirin inhibits COX-1 and prevents platelet aggregation, thereby suppressing EGFR-TKI-associated skin rash." (PMID 40888993, 2025). "Similarly, while skin rash associated with epidermal growth factor receptor inhibitors is partly attributed to inflammatory reactions, topical corticosteroids have been shown to prevent skin rash." (PMID 40810825, 2025). "This case report suggests that PZH Unguentum Compositum may be an effective therapy in treating skin rash caused by EGFR-TKI with fewer side effects." (PMID 36165327, 2022). "The present case report suggests that PZH Unguentum Compositum may be a new option in treating the skin rash caused by EGFR-TKI such as erlotinib." (PMID 36165327, 2022). "Similarly, the mechanism of epidermal growth factor receptor (EGFR) inhibitor-related skin rash is assumed to be associated with inflammatory reactions." (PMID 35836104, 2022). "It was found that the classic clearing-heat TCM decoctions Yin-Qiao powder could significantly improve the skin rashes caused by EGFR-TKIs." (PMID 34646330, 2021). "The objective of this study was to identify epigenetic miRNA associations with therapy-induced skin rash in patients receiving an EGFR targeting tumor treatment, since skin toxicity of EGFRI treatment has been shown to be a prognostic and therapy-predictive factor." (PMID 34012511, 2021). "Interestingly, the severity of skin rash due to EGFR inhibitors has been associated with the better response rate, progression free survival, and overall survival from two large phase III clinical trials." (PMID 27467256, 2016). "Treatment with EGFR inhibitors, such as erlotinib and gefitinib, may cause several types of side effects, including skin rash, acute lung disease, and diarrhea." (PMID 26575584, 2016). "The meta-analysis of the data from these four trials suggests that prophylactic antibiotics might reduce the relative risk of severe rash associated with EGFR-targeted agents by 42–77%." (PMID 23801914, 2013).
Skin rash (continued). "Thus, the role of tumor necrosis factor-α (TNF-α) and interleukin-1 (IL-1) in the development of EGFR inhibitor-associated skin rash was shown and a possible therapeutic role for anti-TNF agents was suggested." (PMID 22761877, 2012). "The host susceptibility to respond in the form of an inflammatory reaction to EGFR inhibition may play an important role in the pathogenesis of EGFRI-associated rash." (PMID 22997576, 2012). "All patients with an EGFR mutation who were assigned erlotinib developed rash." (PMID 23078958, 2012). "Although sunscreen does not have an effect on rash severity, reducing sun exposure can limit the photosensitivity that may be enhanced with EGFR inhibitor therapy, which can add to the symptomatology seen with EGFR inhibitor–associated rash." (PMID 25031940, 2012). "Anti-EGFR monoclonalantibodies and EGFR TKIs are associated with a distinctive skin rash." (PMID 19365583, 2009). "Several studies showed that the skin rash might be associated with the efficacy on EGFR-TKI." (PMID 36165327, 2022). "This meta-analysis demonstrated that addition of EGFR inhibitors to chemotherapy increased the risk of severe toxicity and risk of treatment-related death (although this was numerically small), with an increased incidence of grade 3/4 skin rash and diarrhoea observed." (PMID 28445400, 2017). "Based on indirect comparison it seems that new generation EGFR-TKIs produce a similar response rate to erlotinib or gefitinib with a possible improvement in terms of progression-free survival and with an increased risk of side effects particularly skin rash and diarrhea." (PMID 25505694, 2014). "Focusing on toxicity in elderly patients with EGFR‐mutated NSCLC, previous studies have shown that the incidence of Grade 3 skin rash, diarrhea, and pneumonitis was 14%, 13%, and 2.9%, respectively, with afatinib." (PMID 41350121, 2025). "The main AEs of izalontamab were rash and paronychia, consistent with previous reports of expected on-target toxicities related to the EGFR inhibitors." (PMID 40260627, 2025). "It is also known that the severity of EGFR‐TKI‐induced skin rashes are dose‐dependent, with increased drug exposure leading to increased incidence and severity." (PMID 38379420, 2024). "We have experienced cases of acne‐like skin rash during treatment with EGFR‐TKI, in which the skin disorder improved with the application of adapalene." (PMID 38379420, 2024). "Skin rash (grade 3-4, 24 patients [21%]) and diarrhea (grade 3-4, 9 patients [8%]) were the most frequent adverse events related to the use of anti-EGFR mAbs." (PMID 38592721, 2024). "This is reflected in the emergence of similar toxicities (most frequently skin rashes) upon treatment with EGFR-directed mAbs and TKIs, respectively, despite highly dissimilar mechanisms of action of these two drug classes." (PMID 38492569, 2024). "The administration of minocycline influenced good treatment efficacy with first-line EGFR-TKIs independently of skin rash." (PMID 37221285, 2023). "Since minocycline was administered for skin rash induced by EGFR-TKIs, the timing and duration of minocycline administration depended on adverse events and the treatment duration of EGFR-TKIs." (PMID 37221285, 2023). "One patient in the MINO group and 12 patients in the control group discontinued first-line EGFR-TKIs due to adverse events (hepatic dysfunction, N = 7; skin rash, N = 2; lung injury, N = 2; gastrointestinal toxicity, N = 1; heart failure, N = 1)." (PMID 37221285, 2023). "It is noteworthy that patients who develop skin rash due to EGFR-TKIs are more likely to respond to the treatment, and rash has been found to be an independent predictive factor for improved survival." (PMID 36782147, 2023). "Previous findings demonstrated that the frequency of skin rash induced by osimertinib was less than that with other EGFR-TKIs9,10." (PMID 37221285, 2023).
Skin rash (continued). "Skin rash occurred more often as an adverse event of EGFR-TKIs in the MINO group than in the control group (84.4% vs. 57.5%, p = 0.0062)." (PMID 37221285, 2023). "In the present retrospective cohort study, we showed that the prophylactic or therapeutic administration of minocycline for skin rash prolonged PFS in EGFR-mutant NSCLC patients treated with EGFR-TKIs." (PMID 37221285, 2023). "Recently, vitamin K has emerged as a novel therapeutic candidate for EGFR inhibitor-induced skin rashes." (PMID 38092882, 2023). "In conclusion, the administration of minocycline was identified as a factor that positively contributed to the treatment efficacy of first-line EGFR-TKIs independently of skin rash." (PMID 37221285, 2023). "In the present study, the administration of minocycline prolonged the PFS of EGFR-mutant NSCLC patients independently of skin rash." (PMID 37221285, 2023). "Promotion of CCL5 expression is expected to contribute to the exacerbation of EGFR inhibitor-induced skin rashes." (PMID 38092882, 2023). "Mouse skin in which epidermal EGFR was depleted displayed lesions similar to skin rashes seen in human, while the effect of ablating dermal EGFR has not yet been evaluated." (PMID 37165726, 2023). "There are no clinical trials on the efficacy of menadione and PK in treating EGFR-tyrosine kinase inhibitor (TKI)-related skin rashes." (PMID 38092882, 2023). "EGFR TKI-related skin rash in NSCLC patients correlates with a better treatment outcome than the absence of any grade of skin rash." (PMID 37221285, 2023). "Racial differences in the incidence of skin rashes after EGFR‐TKI therapy have been observed with erlotinib with rates of 82% in Asians and 68% in non‐Asians and with afatinib with rates of 45.8% in Asians and 35.9% in non‐Asians for paronychia." (PMID 37269194, 2023). "Reduction or discontinuation of EGFR inhibitors should be considered when grade 2 rash duration is unmanageable or the patient is unable to tolerate it." (PMID 35223483, 2022). "Here, we report the atrophy of dermal white adipose tissue (dWAT), a highly plastic adipose tissue with various skin-specific functions, correlates with rash occurrence and exacerbation in a murine model of EGFR inhibitor-induced rash." (PMID 35324426, 2022). "A snag of EGFR-targeted therapies is the severe induced skin rash, lymphocytic infiltrates, folliculitis or perifolliculitis, and other related adverse events that they provoke in renal cells and gastrointestinal mucosa." (PMID 36090901, 2022). "Herein, we reported the case of a 50-year-old man who presented with skin rash on the face, head, and back induced by an EGFR-TKI named erlotinib." (PMID 36165327, 2022). "Grade 1/2 skin rashes were the most frequent adverse events, which occurred in 33.3% of the patients who received EGFR-TKI monotherapy and 22.2% of the patients who received EGFR-TKI and crizotinib combination therapy." (PMID 34953403, 2022). "The preventive effect of topical corticosteroids on EGFR inhibitor-related skin rashes has been reported." (PMID 35836104, 2022). "Generally, the acne-like skin rash and pruritus are experienced in 1–2 weeks after starting EGFR-TKI treatment." (PMID 36165327, 2022). "In another study, skin rash induced by EGFR inhibitors was ameliorated by neutralization of IL-8 with a specific mAb." (PMID 36269747, 2022). "Skin toxicities, including acneiform skin rash and nail disorders, are well-known AEs of EGFR inhibitors, and previous meta-analysis from our research group also suggested higher risk of skin toxicities with cetuximab over bevacizumab." (PMID 35954563, 2022). "Herein, we present a successfully treated case of skin rash caused by erlotinib using PZH Unguentum Compositum, in order to provide a new option for EGFR TKI-induced skin rash." (PMID 36165327, 2022).